IL4R (interleukin 4 receptor)
Diseases named in the same sentence as IL4R in open-access papers (continued):
Sharing a sentence is not in itself a finding about the gene and the disease.
medulloblastoma (3 papers, 2002 to 2019). A malignant, invasive embryonal neoplasm arising from the cerebellum. "The cytotoxic activity of cpIL4-PE can be neutralized by either excess IL-4 or IL-13, indicating that IL-4R are related to IL-13R on medulloblastoma cell lines." (PMID 28752098, 2017). "In the present study, we have examined the mRNA and protein expression of various receptor subunits of IL-4R by RT–PCR, radiolabelled binding, and indirect immunofluorescence assays in different medulloblastoma cell lines." (PMID 11870521, 2002). "In conclusion, we report that, like GBM, medulloblastoma cell lines also express IL-4R, which appears to be an efficient target for cpIL4-PE." (PMID 11870521, 2002). "Further studies are required to determine the significance of IL-4R expression on medulloblastoma cell lines." (PMID 11870521, 2002). "Consistent with the expression of IL-4R, cpIL4-PE was found to be highly and specifically cytotoxic to four of five medulloblastoma cell lines." (PMID 11870521, 2002). "We demonstrate that medulloblastoma cell lines express IL-4R that serve as a sensitive target for IL-4R-targeted agent, cpIL4-PE." (PMID 11870521, 2002). "Further studies are warranted to investigate interleukin-4 receptor expression in primary medulloblastoma tumours and sensitivity to cpIL-4PE in vitro and in vivo." (PMID 11870521, 2002). "Our present results confirm those observations and demonstrate that medulloblastoma cell lines also express IL-4Rα and IL-13Rα1 chains in all cell lines tested." (PMID 11870521, 2002). "To determine whether IL-4R on medulloblastoma cell lines could be used as a therapeutic target, we tested sensitivity of these cells to cpIL4-PE." (PMID 11870521, 2002). "As in vitro sensitivity to cpIL4-PE seems to correlate with IL-4R expression and in vivo antitumour activity and medulloblastoma cells expressed IL-4R, we tested whether cpIL4-PE is also cytotoxic to medulloblastoma cell lines." (PMID 11870521, 2002). "The goal of this study was to determine whether human medulloblastoma derived cell lines express interleukin-4 receptor and whether interleukin-4 receptor expression is accompanied by sensitivity to cpIL4-PE." (PMID 11870521, 2002). "IC50 was measured to be 1 ng/mL for three of five medulloblastoma cell lines expressing >900 IL-4 binding sites/cell, 30 ng/mL for D341 cell line expressing ~600 sites/cell, and no marked cytotoxicity at concentrations up to 1000 ng/mL for D283 cell line expressing the lowest level of IL-4R." (PMID 28752098, 2017). "This is different from other reports on medulloblastoma and GBM cells exposed to a single dose (5 Gy) of gamma radiation, where IL-4R decreased." (PMID 30813636, 2019). "It is also not known whether human medulloblastoma cells express IL-4R and, if they do, which chains of these receptors are present on medulloblastoma tumour cells." (PMID 11870521, 2002).
metastatic tumor (3 papers, 2022 to 2024). "IL-4R appears as a plausible candidate to attenuate metastatic tumor growth, especially since previous evidence demonstrated how antibody-mediated IL-4R neutralization lessened metastatic lung tumor burden and IL-4Rα loss reduced metastatic tumor growth." (PMID 37108754, 2023). "Since antibody-mediated IL-4R neutralization and IL-4Rα deletion lowered metastatic lung tumor burden and growth, IL-4R could inhibit metastatic tumor growth." (PMID 38745115, 2024).
multiple sclerosis (3 papers, 2019 to 2023). A progressive autoimmune disorder affecting the central nervous system resulting in demyelination. "These comprise variants within genes associated with various types of human cancer (MAD1L1), Joubert syndrome 23 (KIAA0586), hair disorders (PADI3), mannose-binding lectin deficiency (MBL2), and multiple sclerosis (IL4R)." (PMID 36404349, 2023). "However, looking into our phenotypic data we can verify that CTD (SLC22A5), Parkinson ́s disease (LRPPRC), multiple sclerosis (IL4R), 3-MCCD (MCCC1), and different cancer types (FANCE, MAD1L1 and CD46) have been reported by the participants." (PMID 36404349, 2023). "Finally, a recent study reported the expression of IL-4R surrounding axonal filaments in postmortem brain tissue from patients with multiple sclerosis." (PMID 31226122, 2019). "For example, a recent study reported that the activation of IL-4R signaling in neurons may increase axonal outgrowth and ameliorate axonal pathology in a model of multiple sclerosis." (PMID 31226122, 2019).
myocardial infarction (3 papers, 2014 to 2024). Gross necrosis of the myocardium, as a result of interruption of the blood supply to the area, as in coronary thrombosis. "Interestingly, IL-1, IL-6, CCL2, and CCL3 expression was reduced, whereas Arg1, IL4Rα, and IL-10 expression were increased in macrophages incubated with exosomes derived from the myocardial infarction group." (PMID 35548775, 2022).
renal cell carcinoma (3 papers, 2014 to 2021). "In renal cell carcinoma cells, knock-down of IL4Rα or IL13Rα1 induced cell cycle arrest and apoptosis by suppressing JAK2-mediated phosphorylation of FOXO3." (PMID 33419470, 2021). "In renal cell carcinoma cells, knock-down of IL4Rα or IL13Rα1 and pharmacological inhibition of JAK2 induced cell cycle arrest and apoptosis of cancer cells." (PMID 33419470, 2021). "In renal cell carcinoma cells, the silencing of IL4Rα expression reduced interaction between JAK2 and FOXO3 and resulted in stabilizing FOXO3." (PMID 33419470, 2021).
rhabdomyosarcoma (3 papers, 2021 to 2023). A rare aggressive malignant mesenchymal neoplasm arising from skeletal muscle. "In rhabdomyosarcoma cells, activation of IL4R with IL4 and IL13 ligands increased tumor growth through activation of STAT6, Akt, or MAPK pathways." (PMID 33419470, 2021). "Still, in rhabdomyosarcoma cells, another study showed that tumor cell progression seemed to be regulated by the interleukin-4 receptor (IL-4R)-dependent signaling pathway, highlighting the role of IL-4 in this common type of STS." (PMID 34359785, 2021). "Among the mesenchymal type of cancers such as rhabdomyosarcoma and osteosarcoma cells, it has been suggested that the IL4R pathway might be a therapeutic target of these types of cancers." (PMID 33419470, 2021). "In rhabdomyosarcoma cells, IL4 and IL13 activate cellular proliferation through the JAK/STAT signaling pathway, and blocking IL4R with a neutralizing antibody suppressed tumor progression." (PMID 33419470, 2021).
sarcoidosis (3 papers, 2013 to 2023). Sarcoidosis is a multisystemic disorder of unknown cause characterized by the formation of immune granulomas in involved organs. "Studying the IL-4/IL-4R axis may also be useful to discriminate HP from sarcoidosis, as IL-4R BAL levels appear to differ, but this requires further validation." (PMID 36836922, 2023).
sensitization (3 papers, 2014 to 2020). "First, we assessed the association of FLG variants and IL4R rs3024676 with allergic sensitization to determine their independent effects." (PMID 29459738, 2018). "Hence, we investigated in vivo requirements of IL‐4Rα signaling after allergic sensitization prior to the onset of disease as well as after TH2 pulmonary allergic airway lung inflammation." (PMID 31782803, 2020). "SNPs in or near JAK2, CNOT6, MAML1, CD40, IL-4R, and IL-5RA genes were associated with allergic sensitization and SNPs in or near JAK1, JAK3, IL5RA, FCER1A, and ADAM33 genes were associated with cockroach sensitization." (PMID 25505553, 2014). "In addition, SNPs in or near IL-4R, JAK1, and IL12B showed modest association with allergic sensitization." (PMID 25505553, 2014).
Stroke (3 papers, 2011 to 2024). Sudden impairment of blood flow to a part of the brain due to occlusion or rupture of an artery to the brain. "In this respect, it is encouraging that we did not observe intracranial hemorrhages after stroke in GPIbα/IL4Rα mice." (PMID 21914206, 2011). "Upon assessment of the cerebral vasculature in WT (n = 5) and GPIbα/IL4Rα (n = 3) mice, no major anatomic differences were observed which could influence stroke outcome." (PMID 21914206, 2011). "Since VWF is the main ligand of GPIbα on platelets, our data support the notion of a pathophysiological role for the GPIbα-VWF interaction in stroke, although we can not rule out that other GPIbα-mediated interactions are also important and abrogated in GPIbα/IL4Rα mice." (PMID 21914206, 2011).
visceral leishmaniasis (3 papers, 2014 to 2019). A severe form of leishmaniasis characterized by irregular bouts of fever, substantial weight loss, swelling of the spleen and liver, and anemia (which may be serious). "Consequently, current research within our team is aimed at unraveling IL-4 and IL-13 signaling on specific target immune cells during visceral leishmaniasis using our cell-type-specific IL-4Rα-deficient mouse models." (PMID 29176972, 2017). "In visceral leishmaniasis both, IL-4 and IL-13 play a positive role in granuloma formation and maturation (also pointing to IL-4Rα-dependent inflammatory cell recruitment as found here for pulmonary cryptococcosis) and are essential for optimal development of IFN-γ responses." (PMID 24475277, 2014).
adenoma (2 papers, 1992 to 2013). A neoplasm arising from the epithelium. "In fact, counter-intuitively, smaller IL-4Rα ‘knockout’ tumours exhibited reduced numbers of apoptotic cells compared with WT adenomas." (PMID 23784081, 2013). "A monoclonal antibody (MR6) was applied to detect IL-4R in: metaplastic polyps (five cases), adenomas (15 cases), and carcinomas (44 adenocarcinomas and one squamous cell)." (PMID 1419612, 1992).
AIDS (2 papers, 2014 to 2018). A syndrome resulting from the acquired deficiency of cellular immunity caused by the human immunodeficiency virus (HIV). "Patient-derived AIDS-KS cells can produce IL-4 and express surface IL-4R." (PMID 30619193, 2018).
Airway obstruction (2 papers, 2020 to 2023). Obstruction of conducting airways of the lung. "The increased airway obstruction correlated with modest increases in cellular infiltration in bronchoalveolar lavage (BAL) fluid and lung tissue of Foxp3cre IL-4Rα–/lox mice compared with IL-4Rα–/lox littermate control mice." (PMID 32931477, 2020).
allergic bronchopulmonary aspergillosis (2 papers, 2006 to 2018). Allergic bronchopulmonary aspergillosis (ABPA) is a rare immunologic pulmonary disorder caused by hypersensitivity to Aspergillus fumigatus, clinically manifesting with poorly controlled asthma and recurrent pulmonary infiltrates. "IL-4Rα single nucleotide polymorphisms in asthmatic and cystic fibrosis patients with allergic bronchopulmonary aspergillosis (ABPA)." (PMID 16503977, 2006). "In contrast, in patients with allergic bronchopulmonary aspergillosis (ABPA), A. fumigatus-specific Th2 CD4+ T cells are predominant and a recent work has identified SNPs in genes related with Th2 responses like IL13 and IL4R that increase ABPA susceptibility." (PMID 30459771, 2018).
Alzheimer disease (2 papers, 2018 to 2020). A progressive, neurodegenerative disease characterized by loss of function and death of nerve cells in several areas of the brain leading to loss of cognitive function such as memory and language. "In Alzheimer's disease, CD68 (p = 0.026), CD64 (p = 0.002), CHI3L1 (p = 0.016), IL4R (p = 0.005) and CCR2 (p = 0.010) were increased independently of systemic infection." (PMID 30193587, 2018). "Accordingly, in the DG of the mouse Alzheimer’s disease model, the expression of the interleukin-4 receptor (IL4R) could not be induced in astrocytes." (PMID 33071740, 2020).
anaplastic thyroid cancer (2 papers, 2019 to 2022). "In vitro, IL4R is expressed at high levels on the cell surface of Cal-62 anaplastic thyroid cancer cells." (PMID 36009525, 2022). "Collectively, these findings indicate the feasibility of using IL4RPep-1-EVs as nanocarriers for delivering therapeutic agents in treating anaplastic thyroid cancer and other cancers that express IL4R." (PMID 36009525, 2022). "In the present study, we developed engineered EVs with an IL4R-targeting peptide, which is a new strategy that could be applied in vivo for the treatment of cancers expressing IL4R (including anaplastic thyroid cancer)." (PMID 36009525, 2022). "Furthermore, we exploited the use of EVs that were non-genetically modified with an IL-4R-targeting peptide, IL4RPep-1, using DOPE-BAM to target IL-4Rs in anaplastic thyroid cancer." (PMID 36009525, 2022).
astrocytoma (2 papers, 2016 to 2017). "In previous studies, PIBF (200 ng/mL) increased the number of astrocytoma cells through the activation of the IL-4Rα/JAK1/STAT6 pathway." (PMID 28168193, 2017). "In this subgroup, astrocytoma patients with the AA, AG, and GG IL4R rs1801275 genotypes had 1-year OS rates of 31.0%, 26.0%, and 0%, respectively (P < 0.05)." (PMID 27495027, 2016).
atherosclerosis (2 papers, 2012 to 2022). A disease characterized by the build-up of fatty material and calcium deposition in the arterial wall resulting in partial or complete occlusion of the arterial lumen. "In addition, IL4R is also expressed on atherosclerosis, and it can be used for the treatment of vascular disease." (PMID 36009525, 2022).
bullous pemphigoid (2 papers, 2024 to 2025). Bullous pemphigoid (BP) is the most common form of autoimmune bullous dermatosis. "Dupilumab, a recombinant human IgG4 monoclonal antibody that targets IL-4Rα, has shown promise in treating resistant cases of bullous pemphigoid, including DBP." (PMID 39246960, 2024).
cardiomyopathy (2 papers, 2018 to 2025). A disease of the heart muscle or myocardium proper. "However, a human study points toward a crucial role of the IL-4Rα for developing of cardiomyopathy during Chagas disease, the major complication during the chronic phase of the infection." (PMID 30555475, 2018).
cervical cancer (2 papers, 2025). A primary or metastatic malignant neoplasm involving the cervix. "High levels of IL4R are also linked to an increased risk of cervical cancer." (PMID 40656893, 2025).
Cirrhosis (2 papers, 2023 to 2025). A chronic disorder of the liver in which liver tissue becomes scarred and is partially replaced by regenerative nodules and fibrotic tissue resulting in loss of liver function. "Although a number of inflammatory cytokines and chemokines were differentially expressed in PoPH nuclei as compared to non-PoPH cirrhosis nuclei across multiple clusters, the strongest associations were for increased IL6R and IL4R expression and decreased IL32 expression in PoPH clusters." (PMID 37558836, 2023).
clear cell renal cell carcinoma (2 papers, 2021 to 2022). "Previously we reported that IL4Rα and IL13Rα1 (Type II receptor) is a prognostic marker and involved in the development of clear cell renal cell carcinoma (ccRCC) through JAK2/FOXO3 pathway." (PMID 35207737, 2022). "Especially, clear cell renal cell carcinoma patients with co-positivity for the expression of IL4Rα and IL13Rα1 had the shortest survival time." (PMID 33419470, 2021). "Consistently, although nuclear and cytoplasmic expression were not analyzed separately, higher expression of IL4Rα and IL13Rα1 were significantly associated with shorter cancer-specific survival and RFS of clear cell renal cell carcinoma patients." (PMID 33419470, 2021).
conjunctivitis (2 papers, 2023 to 2025). Inflammation of the conjunctiva of the eye. "Indeed, in accordance with a suggested therapeutic role for IL-4Rα/basophil signaling in our present studies, recent clinical data from a single small study have suggested an increase in basophils associated with conjunctivitis in patients with AD following dupilumab treatment." (PMID 36626228, 2023). "These genes encode for a wide range of biological categories, such as mammaglobin, lipocalin, and secretoglobin, suggesting a possible mechanism occurring at the epithelial layer of the eye that may become exacerbated by anti–IL-4Rα treatment and could underlie conjunctivitis in the clinic." (PMID 36626228, 2023). "Next, we aimed to dissect the possible mechanisms of increased frequency of conjunctivitis in patients with AD treated with dupilumab by exploring the impact of IL-4Rα signaling in our model." (PMID 36626228, 2023). "Our results showed that IL-4Rα signaling contributes to conjunctivitis development in the context of skin inflammation by producing antigen-specific IgE Abs and activating mucosal mast cells and basophils." (PMID 36626228, 2023). "We aimed to develop a mouse model to further understand AD-induced conjunctivitis and to dissect the possible mechanisms of conjunctivitis in patients with AD following dupilumab treatment by exploring the impact of IL-4Rα blockade." (PMID 36626228, 2023). "Our present observations on the therapeutic effect of IL-4Rα blockade in murine experimental conjunctivitis are inconsistent with the increased frequency of conjunctivitis following treatment with dupilumab in patients with AD." (PMID 36626228, 2023). "We concluded the functional role of IL-4Rα signaling in the development of conjunctivitis in response to antigen sensitization and challenge of mice." (PMID 36626228, 2023). "Blockade of IL-4Rα partially attenuated conjunctivitis development, downregulated basophil activation, and led to a reduction in expression of genes related to type 2 cytokine responses." (PMID 36626228, 2023). "Given wide confidence intervals (e.g., dupilumab’s AE ARD spanning the null value), clinical decisions should be balanced against the biological plausibility of mechanism-related risks (e.g., IL-4Rα inhibition and conjunctivitis) and patient-specific factors (e.g., cardiorenal status)." (PMID 41312463, 2025). "Further studies characterizing the biological role of anti–IL-4Rα–augmented pathways that we identified in the mouse model, especially in patients with AD before and during dupilumab treatment, would further reveal our understanding of conjunctivitis." (PMID 36626228, 2023). "To characterize conjunctivitis and the effects of IL-4Rα signaling at the transcriptomic level, we performed RNA-Seq on conjunctival tissues in OVA-challenged mice that received isotype or anti–IL-4Rα treatment, as well as in control mice that were ocularly challenged with PBS (MC903 + OVA/PBS)." (PMID 36626228, 2023). "To complement ongoing phase IV clinical studies to investigate the phenotype and ocular biomarkers of conjunctivitis in patients, we used what we believe to be a novel skin inflammation–evoked conjunctivitis model to further investigate potential effects of IL-4Rα inhibition in mice." (PMID 36626228, 2023). "IL-4Rα blockade partially alleviates conjunctivitis development." (PMID 36626228, 2023). "We speculate the existence of additional mechanisms besides IL-4Rα signaling that mediate conjunctivitis, although a possible mechanism occurring at the epithelial layer of the eye may also become exacerbated by anti–IL-4Rα treatment." (PMID 36626228, 2023). "Since basophils were required for the development of skin inflammation–induced conjunctivitis in mice, we then tested whether targeting IL-4Rα signaling after skin sensitization could affect basophils." (PMID 36626228, 2023).
conjunctivitis (continued). "A subtype of patients with AD may have a predominantly allergic phenotype of conjunctivitis and, thus, the therapeutic effects of IL-4Rα blockade we observed in our preclinical model could reflect this disease phenotype." (PMID 36626228, 2023).